INS (insulin)
Diseases named in the same sentence as INS in open-access papers (continued):
Sharing a sentence is not in itself a finding about the gene and the disease.
Insulin resistance (continued). "At variance, insulin-mediated glucose disposal was significantly improved by L-carnitine only in those patients with greater baseline insulin resistance, selected according to the median value of insulin sensitivity before treatment." (PMID 31547545, 2019). "In contrast, the disruption of LPL in skeletal muscle results in reductions in lipid storage and increased myocyte insulin signalling, together with marked insulin resistance in other tissues, leading finally to obesity and systemic insulin resistance." (PMID 31208038, 2019). "In this study, lactating mice fed CLA displayed aggravated insensitivity to insulin and exhibited insulin resistance, implicating insulin as a key factor in CLA-mediated regulation of milk fat and lactation." (PMID 31390361, 2019). "LepRNull mice showed the expected glucose intolerance, as well as increased insulin resistance and serum insulin concentrations." (PMID 30694175, 2019). "The homeostasis model assessment (HOMA) model is a well-known method used for the quantitative verification of insulin resistance and insulin secretion." (PMID 31252561, 2019). "The transitory increase in insulin resistance during pregnancy activates adaptation processes in β-cells to enhance insulin secretion and maintain normoglycemia." (PMID 31817798, 2019). "Third, insulin resistance and enhanced insulin contribute to the upregulation of betatrophin levels." (PMID 31772689, 2019). "Previously, it was reported that 15 Hz EA at ST36 improves insulin sensitivity and reduces free fatty acid levels in rats with chronic dexamethasone-induced insulin resistance." (PMID 31662781, 2019). "The clinical manifestation of T2DM is characterized by hyperglycemia (prolonged blood glucose level above normal), hyperinsulinaemia (a condition in which there are excess levels of insulin circulating in the blood) along with insulin resistance." (PMID 31499737, 2019). "Insulin resistance is defined as an impaired sensitivity to insulin due to an increase insulin secretion." (PMID 31480505, 2019). "In conclusion, insulin resistance as well as insulin secretion in the KTR group were significantly higher than those in the HC group." (PMID 31252561, 2019). "Hyperphagia can also result from chronic hyperinsulinemia and insulin resistance, which develops in Cc2−/− females at ~2 months of age arising chiefly from increased insulin secretion." (PMID 31266142, 2019). "On the contrary, a genetic variant in DMGDH, causing lower DMGDH, was significantly associated with increased plasma insulin, increased HOMA index of insulin resistance, and increased risk of incident T2DM." (PMID 31208147, 2019). "The decrease in insulin sensitivity that occurs with puberty further compounds insulin resistance in obese adolescents." (PMID 31877943, 2019). "Meanwhile, elevated insulin levels and/or insulin resistance are commonly seen in women with PCOS, and this is one of the most important mechanisms in PCOS pathogenesis." (PMID 31216618, 2019). "Chronic high insulin has been already reported to induce a state mimicking insulin resistance in cortical neurons in vitro." (PMID 29736736, 2019). "Oxidative stress is associated with instigating insulin resistance by up-regulating the production of pro-inflammatory cytokines, such as CRP and TNF-α, which induce damage to proteins in the insulin cascade." (PMID 30723416, 2019). "Several studies indicated that berberine inhibits the mTOR pathway with abnormally high activity in the state of insulin resistance mainly by activating AMPK activity, so as to mediate the insulin signaling pathway and improve insulin resistance." (PMID 31915452, 2019). "T2DM and AD share many characteristics, including chronic inflammation, oxidative stress, impaired insulin signaling, insulin resistance, glucose intolerance, and cognitive impairment." (PMID 30800211, 2019).
Insulin resistance (continued). "T2DM is characterized by high blood glucose, insulin insensitivity as a result of insulin resistance, and impaired insulin secretion." (PMID 31504411, 2019). "In this study we used tracer techniques and continuous glucose monitoring to evaluate changes in glucose fluxes and insulin resistance and understand the mechanisms via which inhaled insulin improves glucose homeostasis in patients with T2D." (PMID 31470605, 2019). "Accumulated studies have strongly suggested miRNAs are essential in regulating pancreatic β cell functions, the release of insulin, and insulin resistance." (PMID 31915414, 2019). "As a further sign of diet-induced insulin resistance, the plasma insulin levels in the sedentary NASH-diet group were significantly higher than in the corresponding sedentary control diet group during the glucose tolerance test." (PMID 31717358, 2019). "Among the contribution of different factors in the development of insulin resistance, the intake of high fat diet has been suggested to reduce the sensitivity of hypothalamic insulin." (PMID 31143098, 2019). "miR-29a has been linked to fatty acid and glucose metabolism, whereas miR-132 was related with incretin-dependent insulin secretion and enhancement of glucose homeostasis, and miR-222 was involved in insulin resistance and pro-atherogenesis." (PMID 31666083, 2019). "The development of insulin resistance in aS6KO mice was confirmed by findings that the levels of insulin-stimulated phosphorylation of Akt (Ser473) in skeletal muscle and liver were significantly lower in aS6KO mice than WT mice." (PMID 31113929, 2019). "Insulin resistance is associated with increased serine phosphorylation of IRS-1 and inhibition of insulin-stimulated IRS-1 tyrosine phosphorylation and AKT activation." (PMID 31396538, 2019). "The T2DM group had the highest index of HOMA-IR and lowest HOMA-IS, but the T2DM+FMT group had largely ameliorated insulin resistance and increased insulin sensitivity." (PMID 32010641, 2019). "These primary effects of TZDs markedly ameliorate insulin resistance and the metabolic syndrome and decrease insulin requirements [18••, 19, 20]." (PMID 31776781, 2019). "Some suggest that IH induces insulin resistance, while some show improvements in insulin sensitivity." (PMID 31455007, 2019). "All subjects performed the euglycemic insulin clamp, and analyses of four fasting insulin resistance indexes: SPISE-IR (= 10/SPISE), QUICKI-IR, Log HOMA-IR, and Revised QUICKI-IR." (PMID 31694444, 2019). "Insulin resistance was induced in vitro in human hepatocyte L-02 cells with 200 mM ethanol for 24 h followed by 10-7 nM insulin for 30 min." (PMID 31555134, 2019). "Together with low insulin levels, the significant reduction in the homeostasis model assessment (HOMA) index, as a measure of insulin resistance, suggests increased insulin sensitivity in Ces2cint mice." (PMID 30766961, 2019). "T2DM is a disease characterized by the inability of the body to produce sufficient insulin, or the development of insulin resistance." (PMID 31888124, 2019). "Insulin resistance and lipotoxicity eventually lead to beta-cell dysfunction with failure to fully counterbalance the increased needs for insulin secretion." (PMID 31417493, 2019). "CYP2E1 knockout mice exhibit a marked protection against high fat diet-induced insulin resistance with enhanced adipose tissue glucose uptake, insulin suppression of hepatic glucose output, and decreased proinflammatory cytokines from adipose tissues." (PMID 31275421, 2019). "IRTKS, as an adaptor protein, has recently been found to bind to IR, leading to enhanced insulin signaling, whereas IRTKS deficiency leads to insulin resistance in mice." (PMID 31212584, 2019). "Our results further support previous findings demonstrating that insulin treatment improves insulin resistance, restores placental insulin and adenosine receptors expression, and positively impacts fetoplacental circulation and endothelial function." (PMID 30873116, 2019).
Insulin resistance (continued). "Autophagy was recently identified to be closely associated with obesity and type 2 diabetes by regulating lipid homeostasis and insulin sensitivity, as defective autophagy promotes ER stress, hepatic steatosis, and insulin resistance." (PMID 31949875, 2019). "Subjects with high subcutaneous fat had lower carbohydrate intakes and better insulin sensitivity, which may be due to consuming less fructose, since fructose consumption has been shown to favor partitioning of fat to the visceral region and is associated with greater insulin resistance as HOMA-IR." (PMID 31719833, 2019). "While acute treatment of myocytes or intravenous infusion of IL-6 to healthy humans increases basal and insulin-stimulated glucose uptake by myocytes and improves whole body insulin sensitivity, chronic action of IL-6 induces insulin resistance." (PMID 30699907, 2019). "Since T2DM is featured in glucose intolerance and insulin resistance, we carried out glucose tolerance and insulin tolerance tests." (PMID 31781248, 2019). "Insulin resistance and insulin sensitivity will be determined using the HOMA-IR and QUICKI equation." (PMID 30832722, 2019). "The possible pathophysiologic mechanisms that provoke insulin resistance in MetS include defective insulin signaling, impaired glucose disposal, lipotoxicity, and inflammatory cytokines." (PMID 31824416, 2019). "Fasting glucose levels, as well as basal and stimulated insulin levels, were significantly higher in aS6KO mice than WT mice, suggesting increased insulin resistance in aS6KO mice." (PMID 31113929, 2019). "A common feature of insulin resistance is hyperinsulinemia, thus excess insulin and glucose would only enhance insulin’s vasoconstricting effects and potentially damage the vessel walls." (PMID 31382355, 2019). "First, insulin resistance-induced increase in insulin level can stimulate cell proliferation and promote mitogenic effects in breast tissue." (PMID 31717292, 2019). "These macrophages were shown to be responsible for producing pro-inflammatory cytokines such as TNFα and IL6, ultimately resulting in impaired insulin signaling, insulin resistance, and cardiovascular diseases." (PMID 31270248, 2019). "It has been shown previously that saturated fatty acid palmitate reduces insulin sensitivity and induces insulin resistance in skeletal muscle." (PMID 31266232, 2019). "At a second stage, exposure to unhealthy lifestyle factors leads to insulin resistance and increased demand on the beta-cells for a compensatory rise in insulin production." (PMID 30971952, 2019). "FTZ also increases the body insulin sensitivity and improves insulin resistance and glucose intake in HepG2 cells." (PMID 30941199, 2019). "Insulin resistance is the hallmark of T2DM and describes a condition whereby the ability of insulin to trigger glucose uptake, metabolism, or storage is impaired." (PMID 31861309, 2019). "Under the condition of insulin resistance, pancreatic β-cells increase the production and release of insulin to maintain the normal glycemia." (PMID 31178685, 2019). "Due to the complications of insulin-sensitizer drugs, alternative remedies in the form of dietary agents to attenuate insulin resistance are receiving more interest." (PMID 31888081, 2019). "In affected patients, hyperuricemia is considered to be caused by reduced renal excretion of uric acid as a consequence of insulin-mediated renal reabsorption of uric acid in the proximal tubules, as a result of insulin resistance." (PMID 32082372, 2019). "For instance, a 30% reduction in body mass index predicts a 50% increase in insulin sensitivity as seen in the European Group for the Study of Insulin Resistance (EGIR) cohort among others." (PMID 31608010, 2019). "In particular, a low response to insulin action in adipose tissue, skeletal muscle, and liver, resulting in insulin resistance, is known as the headstream of metabolic syndrome." (PMID 31192914, 2019).
Insulin resistance (continued). "The primary endpoint was change in glycated hemoglobin (HbA1c), secondary were assessment of blood glucose levels, HOMA-IR (homeostatic model assessment of insulin resistance), insulin, body weight, and blood lipids." (PMID 31721790, 2019). "Low expression of PSAT1 contributes to the progression of insulin resistance through the inactivation of insulin signaling." (PMID 30678306, 2019). "In prediabetic individuals, plasma free fatty acids inhibit insulin-mediated glucose uptake, leading to further insulin resistance and type 2 diabetes." (PMID 31531374, 2019). "Males displayed insulin resistance, through slower glucose clearance despite normal circulating insulin and lower mRNA expression of PIK3R1 and PIK3CB in gonadal fat and liver respectively." (PMID 31300679, 2019). "In the dexamethasone group, there was an increase in serum insulin and homeostatic model assessment of insulin resistance, while total bone mineral density decreased." (PMID 31246234, 2019). "A systematic review of the effect of telmisartan on insulin sensitivity in hypertensive patients with insulin resistance or diabetes was performed." (PMID 30857216, 2019). "The progressive decrease in hepatic Ceacam1 mRNA stems from a compromised ability of insulin to induce Ceacam1 transcription under conditions of hyperphagia-driven insulin resistance and from PPARα activation by lipolysis-derived fatty acids." (PMID 31266142, 2019). "Numerous of in vitro and in vivo studies have pointed out that the role of herbal medicine in improving insulin resistance is related to interventions in various aspects of the insulin signaling pathway." (PMID 31258478, 2019). "This meta-analysis has provided evidence that RS supplementation can improve fasting glucose, fasting insulin, insulin resistance and sensitivity, especially for diabetic with overweight or obesity." (PMID 31168050, 2019). "A statistically significant inverse relationship between vitamin D levels and fasting insulin, 2 h post glucose insulin, HOMA-IR and hs CRP, supporting the close relationship with vitamin D deficiency and insulin resistance." (PMID 31176378, 2019). "Insulin resistance, increased insulin secretion, and lipid accumulation showed in HFD WT mice were improved in HFD KO mice." (PMID 31498850, 2019). "The mutations in Lpin1 resulted in systemic insulin resistance, and downregulation of Lpin1 in C2C12 myotubes via siRNA transfection suppressed insulin action due to the elevated accumulation of intermediate ceramide." (PMID 31338039, 2019). "Impaired insulin signaling and the downregulation of major insulin-responsive glucose transporters are central to insulin resistance in the obese population." (PMID 31249770, 2019). "As shown in this figure, mice in the HFD-L group after week 12 exhibited insulin resistance, with the pancreatic β-cells releasing more insulin in an attempt to compensate, mixed with β-cell failure." (PMID 31383924, 2019). "In summary, the pathway of free fatty acid–induced hepatic insulin resistance is free fatty acids → PKCδ → NADPH oxidase → oxidative stress → IKK-β/JNK → insulin signaling pathway → hepatic insulin resistance." (PMID 31649547, 2019). "Reducing dietary salt helps lower hypertension, less dietary sugar lowers risk of cardiovascular disease and obesity, and a smaller proportion of dietary carbohydrates lowers post-meal insulin response and insulin resistance within one day." (PMID 30678194, 2019). "Knocking out the gene for CB2 resulted in improved insulin sensitivity when investigating age-related or diet-induced insulin resistance." (PMID 31121839, 2019). "Supplementation with a juice made from dried strawberry and cranberry polyphenol extracts for six weeks resulted in significantly improved insulin sensitivity measured by hyperinsulinaemic-euglycemic clamp in subjects with insulin resistance." (PMID 31013914, 2019).
Insulin resistance (continued). "In mice, the administration of selenoprotein P induced hepatic and peripheral insulin resistance, whereas both genetic deletion and RNA interference-mediated knockdown of selenoprotein P ameliorated insulin signaling and improved glucose tolerance." (PMID 31736870, 2019). "Insulin resistance can be defined as the inability of a known quantity of exogenous or endogenous insulin to increase glucose uptake and utilization in an individual as much as it does in a normal population." (PMID 31849810, 2019). "Homeostatic model assessment (HOMA) is a method for assessing insulin resistance (IR) and is a useful index of insulin sensitivity." (PMID 30934943, 2019). "Baseline between group differences were observed in insulin levels and insulin resistance (HOMA IR; both biomarkers p = 0.014)." (PMID 31244668, 2019). "For a given dose of insulin, the peripheral organization or cells cannot respond appropriately, which is known as insulin resistance." (PMID 31344867, 2019). "Although known as a mitogenic factor, exogenous administration of FGF1 results in potent and insulin-dependent glucose lowering effect in insulin resistance mice." (PMID 31920680, 2019). "This reduction in insulin action results in increased inflammation which contributes further to the insulin resistance." (PMID 30873501, 2019). "Insulin resistance can also be determined via the MI, which is calculated based on plasma glucose and insulin levels determined in OGTT." (PMID 31379415, 2019). "Two types of insulin resistance, systemic and hepatic insulin resistance, are defined as the decreased ability of tissues to respond to insulin signals." (PMID 30642126, 2019). "Second, we employed HOMA-IR and HOMA-β as surrogate markers of insulin resistance and insulin secretion as a substitute for hyperglycemic/hyperinsulinemic–euglycemic clamps." (PMID 31764838, 2019). "Oxidative stress driven by hyperglycemia can impair insulin signaling and induce insulin resistance." (PMID 30915195, 2019). "Blocking CCL5/RANTES–CCR5 by genetic deletion or ICV injection of an antagonist inhibited hypothalamic insulin signaling and insulin resistance, indicating that this chemokine has a role in suppressing S6K-mediated negative feedback input to insulin signaling." (PMID 30875909, 2019). "Ceramide induces insulin resistance by antagonizing insulin‐mediated PI3K/AKT signaling, which attenuates glucose metabolism." (PMID 31293078, 2019). "SHORT syndrome is also characterized by partial lipodystrophy and severe insulin resistance (IR), leading to an early onset of type 2 diabetes, due to immediate post-receptor defect in insulin signaling (phosphoinositide-3-kinase regulatory subunit 1-PIK3R1)." (PMID 31583022, 2019). "In Canadian patients, we observe higher insulin secretory capacity, higher estimated insulin resistance but also higher CFRD incidence." (PMID 30894563, 2019). "It is likely that the high expression of MAPK9 is involved in integrating insulin production, insulin resistance, and MAPK and prolactin production signaling to increase lipid synthesis in the liver." (PMID 31456815, 2019). "The aim of the study was to evaluate the relationships between serum fetuin-B concentration and indices of insulin resistance, insulin secretion and markers of liver steatosis in PCOS women in comparison to the control group." (PMID 31307012, 2019). "GLUT4 is widely found in insulin‐ active peripheral tissues, and its downregulation leads to insulin resistance in peripheral tissues." (PMID 31389668, 2019). "The SOCS1, SOCS3, SOCS6 proteins are involved in increasing insulin resistance by inhibiting insulin sensitivity." (PMID 30931309, 2019). "Beta-cell function derived from the oral glucose tolerance setting was calculated as changes in insulin secretion per unit changes in glucose concentration (Btotal) and whole-body insulin resistance using ISIcomposite." (PMID 31164926, 2019).